PARP1 (poly(ADP-ribose) polymerase 1)
Diseases named in the same sentence as PARP1 in open-access papers (continued):
Sharing a sentence is not in itself a finding about the gene and the disease.
cancer (continued). "The ability to trap the PARP1 on DNA differs than the catalytic inhibition and is of clinical importance as inhibitory mechanism leading to the death of cancer cells." (PMID 36094927, 2022). "Based on these results, it is plausible that PARP1 overexpression in cancer would catalytically compromise SET8 leading to slight reduction in H4K20me1 mark." (PMID 36434141, 2022). "Another recent study tested the effect of Olaparib, the inhibitor of poly(ADP-ribose) polymerase-1 (PARP-1) currently used for cancer therapy on the manifestations of chemically-induced experimental colitis in mice." (PMID 35563530, 2022). "Firstly, PARP-1 inhibitors compete with the binding site of NAD+ in the catalytic domain of PARP-1 enzymes and inhibit their activity, leading to an increased error in repair of DNA, particularly in rapidly dividing cancer cells." (PMID 35158955, 2022). "For instance, ARF1, the most altered protein in Stage IV, has been shown to promote BC metastasis; PARP1 has also been demonstrated to enhance metastasis not only in BC but also in other cancer types." (PMID 35453681, 2022). "Olaparib was the first PARP inhibitor approved by the FDA (December 2014) for cancer therapy, and PARP-1 inhibitors have been identified and tested after clinical trials and their function in enhancing the response of cancers to radiation has been documented." (PMID 35053488, 2022). "It is therefore likely that this compound interacts primarily with DNA, causing severe damage; what is more, it blocks the repair of DNA strands in cancer cells, e.g., by degrading PARP1." (PMID 35682740, 2022). "PARP1 is capable of repairing DNA single-stranded breaks, thus compounds that induce PARP1 cleavage can prevent DNA replication and are useful in cancer chemotherapy." (PMID 36349009, 2022). "On the other hand, based on the significant PARP1 trapping capacity, talazoparib has been clinically employed in breast cancer patients with germline mutations of BRCA1/2 and other types of cancer that contain impaired DNA damage responses." (PMID 36497275, 2022). "PARP-1 is best known for its role in deoxyribonucleic acid (DNA) single-strand breaks repair; therefore, PARP-1 inhibition avoids DNA repair and the induction of death of cancer cells." (PMID 35268667, 2022). "Because PARP-1 is involved in many DNA repair pathways and the maintenance of genomic stability, the regulation of PARP-1 activity is an important means for the clinical treatment of related cancers." (PMID 35963853, 2022). "Inhibition of these two PARP1-binding partners prolongs PARP1 trapping and sensitized cancer cells to PARPi." (PMID 36284291, 2022). "Considering the complex interaction between PARP1, HR and other DNA damage repair pathways in the setting of BRCA1/2 mutated cancers, several different mechanisms of resistance have been proposed, although some of them have been only described preclinically." (PMID 35681784, 2022). "This seminal work has led to a wave of clinical approvals for PARP1 inhibitors that are delivering survival benefits to patients with a range of cancers globally." (PMID 34036721, 2022). "PARP1 was reported to be involved in apoptosis induced by oxidative stress and considered as a therapeutic target for cancers." (PMID 36257929, 2022). "PARP1 is an enzyme involved in DNA damage repair and a drug target in BRCA-mutant cancers deficient in homologous recombination repair." (PMID 36483025, 2022). "As PARP inhibitors have been approved for cancer therapy in a variety of cancers, understanding the interactions between PARP1 and CSB is of significant interest." (PMID 36142121, 2022).
cancer (continued). "Poly (ADP-ribose) polymerase-1 (PARP-1) inhibitors are successful cancer therapeutics that impair DNA repair machinery, leading to an accumulation of DNA damage and consequently cell death." (PMID 35158955, 2022). "For more than a decade, inhibition of PARP1 has been a promising therapeutic intervention strategy for cancer." (PMID 36699082, 2022). "In some types of cancer models, it has been reported that PARP1 deletion contributes to a defective activation of transcription factors that play a key role in tumor development, such as NF-kB or hypoxia inducible factor (HIF)." (PMID 35954469, 2022). "SRA737 has also demonstrated synergistic effect with PARP1 inhibitors in cancer both in vitro and in vivo." (PMID 34977872, 2021). "One of the critical functions of PARP-1 is the response to DNA damage, which plays a pivotal role in DNA repair in cancers." (PMID 33805293, 2021). "PARP1-i alone or in combination with platinum-based therapeutics, such as cisplatin, has shown to have antitumor activity in cancers with DNA repair defects." (PMID 33926008, 2021). "Herein, we discuss emerging roles of PARP1 in chromatin remodeling and epigenetic regulation, focusing on its therapeutic implications for cancer treatment and beyond." (PMID 33804735, 2021). "Due to its extensive and pivotal role in DDR, PARP1 has emerged as a promising target for cancer treatment." (PMID 33589610, 2021). "PARP-1 is a protein involved in DNA repair which has been used as a therapeutic target in several human cancers." (PMID 33098490, 2021). "The best-studied PARP, PARP1, is thought to be a key player in these processes and has shown promise as a target for anti-cancer drugs." (PMID 33430384, 2021). "In contrast, cancer cells that have intact or elevated DNA repair capacity are significantly more resistant to PARP1-targeting agents." (PMID 34610973, 2021). "The increased cleaved-caspase 3 and cleaved-PARP1 expression in cancer cells indicates their inability to repair DNA excisions thereby undergoing apoptosis." (PMID 34422720, 2021). "Olaparib and Niraparib are inhibitors of the PARP-1 and -2 enzymes and are able to selectively kill cancer cells that are defective for the BRCA 1 and 2 tumor suppressors." (PMID 33789687, 2021). "In our pan-cancer analysis study, we comprehensively investigated the frequency of PARP1 alterations and their predictive value in a variety of tumor types through an online database." (PMID 34531868, 2021). "PARP1 takes part in various mechanisms leading to the development of resistance to conventional cancer therapy, including radiotherapy, chemotherapy, and hormonal therapy." (PMID 33572647, 2021). "PARP1 also functions as a sensor of oxidative stress, and PARP1 inhibitors have been seen enhancing the cancer cell’s sensitivity towards chemotherapy." (PMID 34199353, 2021). "PARP1 is overexpressed in multiple cancer types including breast cancer, small cell lung cancer, nasopharyngeal carcinoma, acute myeloid leukemia, high-grade epithelial ovarian cancer, and colorectal carcinoma, often with poor outcomes." (PMID 33498235, 2021). "In other words, the mechanism of transcriptional regulation by PARP-1 in cancer cells can be considered as an important function that affects chromatin remodeling, regulation of tumor suppressor or oncogene expression, metastasis, and cancer cell survival." (PMID 33805293, 2021). "PARP1 is the target of clinically approved anti-cancer drugs whose in vivo efficacy has been hard to predict." (PMID 33531508, 2021). "High PARP1 expression in tumor cells was significantly correlated with shorter cancer-specific overall survival (p = 0.015) in lymph node-negative patients." (PMID 33572647, 2021). "Largely overlooked, in the context of cancer, is the inhibitory effect of 2-PY on PARP-1 activity, which abrogates NNMT’s positive effect on cellular NAD+ flux by stalling liberation of NAM and reducing NAD+ synthesis in the salvage pathway." (PMID 34073600, 2021).
cancer (continued). "Several PARP1 inhibitors have been successfully developed, with Olaparib being the first one to be approved clinically for treating BRCA1/2-mutated cancers." (PMID 34445442, 2021). "Accumulating evidence reveals that excessive activation of PARP-1 contributes to the pathogenesis of many diseases including cancer and neurodegenerative disorders." (PMID 34206804, 2021). "As predicted, PARP1, one of the most representative cellular substrates of caspase-3 during apoptosis, was cleaved when si-MDC1 was transfected in BIN1-deficient cancer cells in the presence of cisplatin." (PMID 34948122, 2021). "Impaired homologous recombination (HR) DNA repair in cancer cells would render synthetic lethality with PARP1 inhibition." (PMID 34734468, 2021). "As indicated by western blot analysis, treatments with T-96 resulted in more Cleaved-PARP1 and Bax proteins, but decreased expression of Bcl2, Survivin and PARP1 in the cancer cells when compared with the control group." (PMID 34093803, 2021). "In particular, HT inhibits homologous recombination, induces BRCA2 degradation, sensitizes cancer cells to poly(ADP-ribose) polymerase-1 inhibition, and affects DNA-PKCs." (PMID 34201993, 2021). "Through blocking this protein-protein interaction, CAM833 is able to prevent RAD51-mediated homologous recombination and thus potentiate cancer cells to damage by radiation or PARP1 inhibition." (PMID 33662256, 2021). "PARP-1 is well studied in human diseases such as cancer, central nervous system (CNS) disorders and pathology of RNA viruses." (PMID 34698261, 2021). "Recently, cellular ADPr levels have been proposed as a biomarker that positively correlates with PARP1/PARP2 inhibitor sensitivity across certain types of cancer cells." (PMID 34210965, 2021). "The somatic mutation in the PARP1 is also known to affect the response to PARP inhibitors, helping to select a useful treatment strategy in various cancers." (PMID 34065872, 2021). "Taken with PARP1 involvement in regulating AR transcriptional activity, the loss of PARP1 in ERG fusion positive cancers would disrupt ERG expression and transcriptional activity." (PMID 34208794, 2021). "Our study supports the existing perception that β-lap is an NQO1 bioactivatable drug, and β-lap’s lethality stems from β-lap-induced futile redox cycling in NQO1+ cancer cells, producing oxidative DNA lesions and consequent PARP1- mediated necrotic cell death." (PMID 34789190, 2021). "PARP1 has been shown to contribute to the progression of some cancers due to its fundamental role in cellular events, such as DNA damage repair, transcription, cell cycle progression, unfolded protein response, and cell death." (PMID 33525741, 2021). "MortaparibPlus-induced cytotoxicity to cancer cells is mediated by multiple mechanisms that included the inhibition of PARP1, up-regulation of p73, and down-regulation of mortalin and CARF proteins that play critical roles in carcinogenesis." (PMID 33671256, 2021). "PARP-1 inhibitors are mentioned as one of the treatment options for cancer—as they influence the stabilization of the genome and repair of DNA mutations." (PMID 33572586, 2021). "This is supported by studies reporting limited tumor growth of PARP-1/PARP-2 proficient cancer cell lines in PARP-1 or PARP-2 knockout host mice." (PMID 33923319, 2021). "On the other hand, POPA was the best augmenter of the PARP1/ACTB mRNA ratio in BRCA1-null UWB1.289 cancer cells." (PMID 34440232, 2021). "Then, EVs of cancer origin were used to carry the CRISPR system targeting poly (ADP-ribose) polymerase-1 (PARP-1) gene." (PMID 34203051, 2021).
cancer (continued). "Regorafenib’s anti-cancer effect, i.e., induction of apoptosis was further demonstrated at the protein level, by activation of PARP-1 cleavage protein expression in a dose-dependent manner when compared with control co-culture cells." (PMID 34638417, 2021). "Phosphorylation of PARP1 at Tyr907, mediated by c-Met, increases PARP1 enzymatic activity and reduces its binding to PARPi, thereby rendering cancer cells resistant to PARPi." (PMID 34702316, 2021). "PARP-1 inhibitors are already used in the treatment of certain types of cancers—ovarian, breast, and prostate." (PMID 33572586, 2021). "These cellular processes contributed by PARP-1 can result in malignant transformation, and the cancer cells would be more likely to adapt better even under unfavorable conditions to survival." (PMID 33805293, 2021). "Here we show that, in the absence of XRCC1, PARP1 can become excessively engaged on BER intermediates in a manner similar to that induced by anti-cancer PARP1 inhibitors, demonstrating that PARP1 trapping is a threat to normal genome integrity." (PMID 34102106, 2021). "One of the roles of PARP1 in the DDR is to recruit the ALC1 (activated in liver cancer 1) protein, amplified in over 50% of HCC tumours." (PMID 34440228, 2021). "Regulation of PARP-1 expression and activity is shown to be important in cancer, cell metabolism, stress response, DNA damage, and neuronal differentiation and signaling, in addition to drug abuse." (PMID 34698261, 2021). "PARPs generating PAR modifications include PARP1/2 and the tankyrases, both of which are targets for cancer therapy." (PMID 34639169, 2021). "PARP-1 can also immediately regulate the sequence-specific transcription factors that are highly relevant for malignant tumor formation." (PMID 33805293, 2021). "Although we found that activation of PARP1 contributes to the rapid decline of glycolytic activity in irradiated cancer cells, presumably as a consequence of IR-induced DNA damage, the mechanisms underlying the mitochondrial shutdown remained elusive." (PMID 34825138, 2021). "Since 2009, when a first-in-human clinical trial of olaparib confirmed the synthetic lethal interaction between inhibition of PARP1, a key sensor of DNA damage, and BRCA1/2 deficiency, PARPi therapies have been approved for the use in several cancers." (PMID 33800556, 2021). "The closest relationship between PARP-1 and proliferation exists in the DNA replication process itself, as evidenced by the destabilization of replication forks in PARPi-treated cancer cells." (PMID 33922595, 2021). "PARP-1 radiotracers with high affinity and selectivity, and appropriate in vivo pharmacologic properties, can serve as robust biomarkers for monitoring cancer progression, metastasis, and evaluating PARP-1 related oncologic interventions." (PMID 34069967, 2021). "DDR gene alteration induces a dependency on poly(adenosine diphosphate-ribose) polymerase (PARP)-1 for DNA repair, leading to cancer cell death when PARP-1 is inhibited." (PMID 33781305, 2021). "In this regard, the inhibitor of PARP1, Ola, is in trials for several human cancers including ovarian cancer, prostate cancer; and breast cancer." (PMID 34447970, 2021). "Numerous PARP1 inhibitors have been developed, and their efficacy in cancer treatment is attributed to both the inhibition of enzymatic activity and their ability to trap PARP1 on to the damaged DNA, which is cytotoxic." (PMID 33361107, 2021). "PARP-1 inhibition represents a current strategy for cancer treatment to prevent heightened AP-1 activation." (PMID 34193871, 2021). "PARP1 inhibitors are originally used for targeting the homologous recombination repair defects in cancers, and mainly categorized as oncology drugs." (PMID 33895786, 2021).
cancer (continued). "While PARP1 is clearly involved in all ten cancer hallmarks, an increasing body of evidence supports the role of other PARPs in modifying these cancer hallmarks (e.g., PARP5a and 5b in replicative immortality and PARP2 in cancer metabolism)." (PMID 33922595, 2021). "For example, silencing PARP16 in vitro reduced cancer cell survival when cells were treated with the PARP1 inhibitor Olaparib and the WEE1 inhibitor adavosertib." (PMID 35096828, 2021). "We hope that this discovery can develop possible PARP1 nuclear metastasis inhibitors and test its possibility as cancer treatment drugs." (PMID 34199353, 2021). "In order to explore the relationship between PARP1 and OXA resistance, we inhibited PARP1 to significantly enhance the ability of OXA to kill cancer and OXA resistance cells." (PMID 34497808, 2021). "PARP16 has been identified as a potent novel target for cancer therapeutics when inhibited in conjunction with PARP1." (PMID 35096828, 2021). "We hope that through this research, we can further analyze the correlation between cell cycle control and DNA repair, and provide another type of PARP1 activation mechanism for cancer treatment strategies." (PMID 34199353, 2021). "To further explore the notion that ICMT function is essential in supporting ERK-dependent DNA damage repair and the potential application in cancer treatment, we evaluated the effect of concurrent suppression of PARP1 and ICMT." (PMID 34610973, 2021). "It has been shown that inhibition of PARP1 sensitizes cancer cells to oxidative stress, suggesting a potential therapeutic strategy to kill cancer cells by combining PARPis and pro-oxidant agents." (PMID 35155204, 2021). "PARP1, a chromatin-bound nuclear enzyme that is activated by DNA damage, is a validated therapeutic target for cancers and other human diseases." (PMID 34408776, 2021). "IR and cDDP both lead to cancer cell death, primarily by inducing DNA damage, whereas PARP1-i, HT and also cDDP inhibit or disturb the DNA repair pathways." (PMID 33926008, 2021). "β-lap was reported to induce cancer cell death via an NQO1-dependent programmed necrotic pathway, which caused robust ROS elevation and PARP1 hyperactivation." (PMID 34676172, 2021). "The present review discusses the multiple functions of PARP1 in normal and cancer cells, expanding on its emerging role as a novel therapeutic target for clinical applications." (PMID 33804735, 2021). "From cancers to respiratory diseases, PARP1 offers alternative approaches for the development of novel therapeutic strategies." (PMID 33804735, 2021). "PARP-1 also has widespread functions that are essential for the survival and growth of cancer cells." (PMID 33805293, 2021). "There is evidence that the enzyme and transcription functions of PARP-1 increase as the disease progresses, and are unrelated with DNA repair in cancer." (PMID 34777465, 2021). "The selective and enhanced PAR-induced cellular lethality following co-treatment of a PARG inhibitor with NRH can feasibly result from either enhanced global DNA damage and/or enhanced replication stress in cancer cells, both known to activate PARP1." (PMID 34806016, 2021). "Several inhibitors of the enzymatic activity of PARP-1 (PARPi) are already used in clinical practice for the treatment of cancer." (PMID 34768872, 2021). "BRCA1-null UWB1.289 cancer cells transcribe a significantly higher PARP2 (t-test, p < 0.001) and a strikingly lower PARP1 mRNA content (t-test, p < 0.001) due to the BRCA1 loss of activity." (PMID 34440232, 2021). "Of these 18 members, the most relevant ones in the context of cancer appear to be PARP1 and PARP2, recognized for their ability to activate base excision repair (BER) in response to single-stranded DNA breaks (SSBs)." (PMID 34880756, 2021). "Either PARP-1 or CAF-1/p60 overexpression has been reported in multiple types of cancer, and this has been related to histopathological grade and/or adverse clinical behavior." (PMID 33098490, 2021).